ULBP1 (UL16 binding protein 1)
Diseases named in the same sentence as ULBP1 in open-access papers (continued):
Sharing a sentence is not in itself a finding about the gene and the disease.
osteoporosis (1 paper, 2024). A condition of reduced bone mass, with decreased cortical thickness and a decrease in the number and size of the trabeculae of cancellous bone (but normal chemical composition), resulting in increased fracture incidence. "Our data suggested that ULBP1 presented to be upregulated in serum of osteoporosis, while downregulated in hMSCs with higher osteoblast differentiation." (PMID 38481217, 2024). "The protein levels of ULBP1 were also found to be elevated in serum samples of patients with osteoporosis." (PMID 38481217, 2024). "The ULBP1 gene has been identified in the osteoclast precursor cells sorted from the circulating monocytes of patients with osteoporosis and normal controls according to the bioinformatic analysis." (PMID 38481217, 2024). "UL-16 binding protein 1 (ULBP1) gene was upregulated in osteoporosis and downregulated in differentiated hMSCs." (PMID 38481217, 2024). "In this study, ULBP1 gene has been identified to be overexpressed in osteoporosis patients whereas was down-regulated in differentiated hMSCs." (PMID 38481217, 2024). "Earlier bioinformatics analysis results suggested that ULBP1 may be a regulatory DEGs in osteoporosis, which was also verified in this study." (PMID 38481217, 2024). "In addition, mRNA expression of ULBP1 was also over-expressed in serum of osteoporosis patients whereas suppressed in osteogenic differentiated hMSCs." (PMID 38481217, 2024). "ULBP1 may be a the Achilles’ heel of osteoporosis, and suppression of ULBP1 could be a promising treatment for osteoporosis." (PMID 38481217, 2024). "However, the effects of ULBP1 in osteoporosis remain unreported." (PMID 38481217, 2024). "Knockdown of ULBP1 may be an alternative for the treatment of osteoporosis." (PMID 38481217, 2024). "ULBP1 is one of the ligands of natural killer group 2 member D (NKG2D) and mediates natural killer (NK) cell cytotoxicity, and has been identified to be a DEGs in osteoporosis." (PMID 38481217, 2024).
osteosarcoma (1 paper, 2022). A usually aggressive malignant bone-forming mesenchymal neoplasm, predominantly affecting adolescents and young adults. "Decitabine could upregulate major histocompatibility complex class I-related chains B and UL16-binding protein 1 expression, and combination treatment involving γδ T cell immunotherapy and decitabine could be used to enhance the cytotoxic killing of osteosarcoma cells by γδ T cells." (PMID 36518755, 2022).
prostate tumor (1 paper, 2015). "The prostate tumor cell lines expressed high levels of MICA/B and ULBP1/2/3, which are ligands for the activating receptor NKG2D, and these observations were confirmed through detection with NKG2D-Fc recombinant protein." (PMID 25961317, 2015).
rheumatoid arthritis (1 paper, 2017). A chronic, systemic autoimmune disorder characterized by inflammation in the synovial membranes and articular surfaces. "Notably, we found that the induction of the NKG2DLs ULBP1-3 expression was specific for SLE serum, since serum from patients with Sjogren syndrome, systemic scleroderma or rheumatoid arthritis did not induce the expression of NKG2DLs on Treg cells." (PMID 28455530, 2017).
uveal melanoma (1 paper, 2020). A melanoma derived from melanocytes of the uveal tract. "MIC-A, MIC-B and ULBP1–3 have been reported in uveal melanoma cell lines." (PMID 33317028, 2020).
ZIKV infection (1 paper, 2019). "Finally, we found a trend in the down modulation of ULBP1 mRNA (p = 0.250) by ZIKV infection that was not confirmed at protein level." (PMID 31547470, 2019).
tumor (102 papers, 2010 to 2025). "Several studies have linked a better prognosis to ULBP1 expression on tumor cells in the context of cancer." (PMID 39866909, 2024). "In the context of leukemia and lymphoma cell recognition by Vγ9Vδ2+ T cells, it was reported that tumor-expressed ULBP1 was a strong marker for tumors susceptible to Vγ9Vδ2+ T cell-mediated cytotoxicity." (PMID 35880177, 2022). "In studies of HCC, soluble MICA expression has been associated with poor prognosis; conversely, expression of ULBP1 on the tumor surface has been associated with improved survival." (PMID 32656081, 2020). "Here, we demonstrated that tuvusertib treatment increased tumor cell lysis by HD and PCa patient NK cells and is associated with increased surface expression of ULBP-1, an NKG2D ligand, on DU145 cells and the death receptor TRAIL-R2 on both DU145 and 22Rv1 cells." (PMID 41417226, 2025). "Immunohistochemical staining of tumor tissue for ULBP1 combined with serum measurement of ULBP1 may be able to demonstrate a correlation between ULBP1 loss at the cell surface and ULBP1 presence in serum." (PMID 32656081, 2020). "We observed a significant downregulation of NKG2D ligands, such as MICA, MICB and ULPB1, 2, and 3 following BET/JQ1treatment of the human tumor cells with similar findings noted in mouse N2a treated cells as well (Ulbp1, Rae1a and Rae1b)." (PMID 40552293, 2025). "The COAD tumor samples showed an increase between 4.5 and 11.3-fold for ULBP1/2/3/6 compared to normal tissues, and MICA and MICB had expression increases of 1.29 and 1.89-fold." (PMID 40013140, 2025). "This inability in separating the abundances of activating ligands can be associated with the inability of NK cells to respond to infected or tumor target cells expressing higher abundances of activating ligands such as ULBP1–6 or MICA/B." (PMID 40196617, 2025). "Valproic acid enhances CAR-T cell recognition of tumor targets and cytotoxic effects by upregulating the expression of NKG2D ligands (ULBP1-3) on tumor cell surfaces and activating the NKG2D-NKG2DL immune recognition axis." (PMID 40657246, 2025). "To further evaluate the roles of these genes in tumor recognition and immune response, we examined the expression levels of their corresponding ligands, Ulbp1 (ligand for NKG2D) and Cd48 (ligand for 2B4/SLAMF4), on BLMP1/2A cells and T-ALL tumor cells." (PMID 40534857, 2025). "As ULBP1 is widely expressed in dysplastic nodules in moderately differentiated HCC, tumor development and early recurrence are associated with its decreased expression." (PMID 39866909, 2024). "In tumor cells, ligands of ULBP1, ULBP2/5/6, ULBP3, ULBP4, and MICA/B can bind to NKG2D receptors among tumor-activating receptors of NK cells." (PMID 39339179, 2024). "Research has demonstrated that radiotherapy at a dose of 20 Gy can increase the expression of MICA/B and ULBP1/2 on the surface of tumor cells, and, co-culture with these tumor cells can enhance the cytotoxicity of NK cells." (PMID 38162672, 2023). "In HCC tumor tissues, overexpression of ULBP1 can recruit NK cells to the tumor and leads to immune escape when accompanied by PD-L1 expression." (PMID 36300115, 2022). "The validation result based on the Guangxi cohort found that the expression level of ULBP1 gene in COAD tumor tissue was significantly higher than that in adjacent normal tissues (p = 0.0028)." (PMID 35211154, 2022). "Our findings showed that dramatic downregulation of exosomal PD-L1, E-cadherin, ULBP1, ULBP3, MICA, MICB, Siglec7 and significant upregulation of exosomal PD-1 and IFN-gamma were associated with tumor regression." (PMID 36741391, 2022).
tumor (continued). "The results showed that the expression level of ULBP1 gene in COAD tumor tissues was significantly higher than that in adjacent normal tissues (p < 0.001)." (PMID 35211154, 2022). "It was also found that the expression level of ULBP1 in most tumor tissues was higher than that in normal tissues adjacent to cancer." (PMID 35211154, 2022). "Similar to Vδ2+ γδ T cells, the NKG2D-expressing Vδ1+ γδ T cells can be activated by stress-inducible MICA/MICB and ULBP1–6 family proteins, which are frequently upregulated in tumor cells." (PMID 35880177, 2022). "In these immunostimulatory marker genes, CD276, MICB, NT5E, PVR and ULBP1 had a significantly positive correlation with RRM2 expression in most tumor types." (PMID 35740608, 2022). "The expression level of ULBP1 gene was related to the tumor grade and prognosis, and the differential expression level of ULBP1 gene was different in tumor tissues and adjacent normal tissues of patients with different tumor stages." (PMID 35211154, 2022). "The proportion of ULBP1+ cells, TC or NKc had a significant increase in tumor tissues compared with peritumor tissues." (PMID 34568062, 2021). "Combined survival analysis showed that only ULBP1 and PD-L1 in tumor tissues possessed a significant prognostic signature for patients with HCC." (PMID 34568062, 2021). "In turn, the high ULBP1 group in both tumor tissues (p < 0.001) and peritumor tissues (p < 0.001) had more PD-L1+ cells than the low ULBP1 group." (PMID 34568062, 2021). "The colocalization of ULBP1 and PD-L1 was also observed in the TC of tumor tissues, which was also confirmed in the HCC cell lines MHCC97H and PLC/PRF/5." (PMID 34568062, 2021). "HCC patients with high ULBP1 in tumor tissues had a significantly shorter OS than those with low ULBP1 (p < 0.01), and ULBP1 in peritumor tissues was also significantly related to the OS of patients (p = 0.03)." (PMID 34568062, 2021). "Combined survival analysis indicated that patients with high ULBP1 and high PD-L1 in tumor tissues had the worst prognosis, while patients with low ULBP1 and low PD-L1 had the best prognosis." (PMID 34568062, 2021). "The ULBP1 concentration in the tumor-conditioned media reached a similar high level to that found in the sera of HCC patients (5041 pg/ml), whereas the concentration in the conditioned media from surrounding liver was negligible (202 pg/ml)." (PMID 32656081, 2020). "In HCC, hsa_circ_0085154 promoted ULBP1 expression and assisted NK cells to recognize target tumor cells." (PMID 33614486, 2020). "Expression of ULBP1 was increased 420% by percent positive among tumor cells (p = 0.008) and 43% by MFI (p = 0.03)." (PMID 32499867, 2020). "In addition it will be revealing to understand whether other histological features of the tumor including histological subtype, vascularity and immune infiltration are associated with ULBP1 secretion as these may provide insights into the mechanism of ULBP1 production and shedding." (PMID 32656081, 2020). "Future work should combine measurement of serum ULBP1 with phenotypic and functional assessment of tumor-infiltrating NK cells." (PMID 32656081, 2020). "Among the NKG2DLs MICA/B and ULBP1/2/3, the expression levels of MICA/B in BC tissues were inversely associated with the Tumor Node Metastasis stage." (PMID 28383557, 2017). "Our data suggest that RBM4 further promotes tumor suppression by favoring the canonical splicing of ULBP1 mRNA, marking cells for elimination by the immune system." (PMID 26565589, 2015). "The results suggest that ATF4 drives basal ULBP1 expression in multiple tumor cell lines, perhaps reflecting constitutive activation of underlying stress pathways." (PMID 26565589, 2015).
tumor (continued). "One of the well-studied activating receptors recognizes a number of proteins and molecules that are produced by abnormal or tumor cells, including a protein called ULBP1." (PMID 26565589, 2015). "Increased ATF4 expression has been detected in some tumors, providing a possible mechanism for coupling malignant transformation to expression of ULBP1, and consequently to tumor immunosurveillance." (PMID 26565589, 2015). "Among these markers, expression of ULBP1 was significantly different depending on patient tumor stage (p = 0.010) and tumor size (p = 0.045)." (PMID 25510288, 2014). "Strong expression of Vδ1+ T cell target NKG2D ligands (NKG2DL) ULBP-2 and ULBP-3 and moderate expression of ULBP-1 was noted on both tumor cell lines." (PMID 23950874, 2013). "Taken together, these data support that CuET stimulates i) NKG2D receptor expression on NK and T cells and ii) NKG2D ligand expression, such as MICA/B and ULBP1/2, on tumor cells, thereby facilitating immune recognition and more effective elimination of tumor cells by cytotoxic effector cells." (PMID 40013140, 2025). "NK cells express NKG2D receptors that bind to ULBP1/2 ligands on the tumor cell surface." (PMID 37602328, 2023). "Likewise, MICA/B and ULBP1 were abundantly expressed, with more than 75 and 57% of the bone metastatic samples showing the expression of these markers in more than 50% of the tumor cells, respectively." (PMID 37134157, 2023). "Changes in the expression level of ULBP1 are inseparable from tumor differentiation and grade." (PMID 35211154, 2022). "In other words, ULBP1 is closely related to tumor prognosis." (PMID 35211154, 2022). "Similarly, it was shown that ULBP1 overexpression in tumor cells can lead to enhanced killing by Vγ9Vδ2+ T cells." (PMID 35880177, 2022). "Furthermore, circARSP91 interacts with UL16 binding protein 1 (ULBP1) in the HCC cell line leading to activation of the natural killer cells (NK cells) and increase in the tumor cells’ susceptibility to NK cells." (PMID 34449657, 2021). "Pearson correlation analysis suggested that a significant association of ULBP1 with PD-L1 or CD56 was observed in tumor tissues but not in peritumor tissues." (PMID 34568062, 2021). "NKG2D was not downregulated on peripheral NK or CD8 T cells in the context of detectable ULBP1, but may have been affected within the tumor micro-environment, where NKG2D is known to be significantly downregulated." (PMID 32656081, 2020). "We therefore proposed that EMT might be involved in the immune escape of CTCs from natural killer (NK) cell killing through altered expression of ULBP1 on the tumor cells." (PMID 32077634, 2020). "Similarly, in cancer patients, the presence of MICA- and ULBP1-expressing myeloid cells in blood and tumor correlated with reduced NKG2D expression on NK cells." (PMID 29740438, 2018). "Additionally, western blotting showed that the MICB and ULBP1 proteins in OS tumor tissues increased after DAC treatment." (PMID 29910819, 2018). "We speculate that tumor cells are under selective pressure to downregulate RBM4 expression, as this would allow tumors to evade tumor-suppressive events such as expression of Bcl-xS and ULBP1." (PMID 26565589, 2015). "However, ULBP1 may be secreted by certain tumor cells and released into the surrounding environment." (PMID 39866909, 2024). "However, it is notable that ULBP1 is an NKc activator and could recruit NKc and T cells to the tumor, which can eliminate tumors directly." (PMID 34568062, 2021). "In line with the relevance of NKG2D/NKG2D-L interaction in tumor control there is the recent observation that gastric circulating tumor cells (CTC) undergoing epithelial to mesenchymal transition (EMT) downregulate ULBP1, thus possibly favoring metastatic growth by evading NK-mediated killing." (PMID 33321719, 2020).
tumor (continued). "Studies have shown that the expression of TGF-β and NKG2DL (MICA/B, ULBP1–3) on the exosome surface in the extrapleural fluid of malignant mesothelioma downregulates the expression of NKG2D on immune cells, which is also an important factor causing tumor immune escape." (PMID 30813924, 2019). "Stress-induced ligands, such as ULBP1, CD155, and CD112, are frequently upregulated in tumor cells and are recognized by NK cell receptors like NKG2D, NKp30, and NKp44, thereby providing an additional anti-tumor mechanism." (PMID 40317083, 2025). "All three datasets saw a statistically significant upregulation of ULBP1/2 and CD276 in tumor samples versus adjacent normal tissue." (PMID 40013140, 2025). "When examining the effect of CuET on NKG2DLs expressed in human tumor cell lines (HCT116 and HT-29), we observed effective upregulation of MICA/B and ULBP1/2 at the mRNA and protein levels." (PMID 40013140, 2025). "Their corresponding ligands, Ulbp1 and CD48, were highly expressed on the tumor cell surface, providing crucial activation signals for CD8+ T cell recognition of MHC class I-low or -negative tumors." (PMID 40534857, 2025). "We examined the surface expression of MICA/B, ULBP1, ULBP2/5/6 and ULBP3 on SKOV-3, BT-474 and MCF-7 tumor cells growing in 3D culture after spheroid dissociation." (PMID 39457710, 2024). "Currently, it has been found that ULBP1 activates NKG2D receptors on the surface of some T cells and natural killer cells to mediate anti-tumour immunity." (PMID 38331839, 2024). "Because neoplasms are able to release NKG2D ligands MICA/B and ULBP1/2/3 by proteolytic cleavage, and thus evade NKG2D-mediated NK cell cytotoxicity." (PMID 36980527, 2023). "Tumor cells and primary MM cells treated with DRd for 24 h showed significantly increased expression of MICA, MICB, ULBP1, ULBP2, and Fas receptor compared to Rd or untreated tumor cells (all p < 0.0001)." (PMID 36385211, 2023). "We found the mRNA expression level of MICA, MICB, ULBP1, ULBP2, ULBP4, and ULBP5 was significantly higher in tumor tissues than that in adjacent normal tissues, whereas ULBP3 expression was lower in tumor tissues compared to adjacent normal tissues." (PMID 36210637, 2023). "GSK343 treatment decreased DNMT3A recruitment to the ULBP1 ligand promoter, reducing promoter DNA methylation and increasing ULBP1 expression, further elucidating the role of EZH2 as an inhibitor of anti-tumor immune responses." (PMID 37090711, 2023). "The protein expression pattern of MICA/B, ULBP1, ULBP3, and ULBP4 between paired tumor and adjacent tissues was consistent with that in mRNA levels of the TCGA‐LIHC dataset." (PMID 36210637, 2023). "The levels of the total ligands MICA, ULBP1, and HLAE were increased in more advanced tumor patients." (PMID 36931723, 2023). "In this study, a total of 456 patients with ULBP1 mRNA expression data set in COAD were obtained from the TCGA database, including 480 tumor tissue samples and 41 adjacent normal tissue samples." (PMID 35211154, 2022).